EGFR (epidermal growth factor receptor)
Diseases named in the same sentence as EGFR in open-access papers (continued):
Sharing a sentence is not in itself a finding about the gene and the disease.
tumor (continued). "However, the mean expression levels of circulating miR-504 in ALK-positive patients (11.41 for miR-191 normalised data; 15.38 for miR-16 normalised data) were clearly lower than in EGFR-mutated subjects (13.24 and 17.01, respectively), which is consistent with the trend observed in tumour tissue." (PMID 30953094, 2019). "However, osimertinib has demonstrated a greater penetrating capacity of the mouse BBB compared with gefitinib, rociletinib, and afatinib, and could achieve sustained tumor regression in an EGFR mutated PC9 mouse model of BM." (PMID 31399067, 2019). "In the ASSESS study, we observed high concordance of mutation status between matched biopsy/cytology and plasma samples, suggesting that circulating free tumor-derived DNA (ctDNA) can be isolated from the plasma or serum and could serve as a feasible sample for real-world EGFR mutation analysis." (PMID 29623586, 2018). "Therefore, we predicted that PD-L1 might make a significantly greater contribution to tumor malignancy in patients with EGFR-mutated NSCLC tumors than with EGFR-WT tumors." (PMID 29435131, 2018). "Finally, EGF‐containing fibulin‐like extracellular matrix protein 1 (EFEMP1), which binds to epidermal growth factor receptor (EGFR) to promote tumor growth, invasion, and metastasis, showed a threefold increase across seven O‐linked glycosylation sites in tumor tissue." (PMID 30459171, 2018). "Thus, ERK activity dynamics are defined by composite inputs from EGFR and ErbB2 signalling in IECs and their alterations might underlie tumour-specific sensitivity to pharmacological EGFR inhibition." (PMID 29872037, 2018). "Our data reveals that USP17 facilitates trafficking and oncogenic signaling of mutant EGFR and indicates targeting USP17 could represent a viable therapeutic strategy in NSCLC tumours carrying either an EGFR activating mutation, or a resistance gatekeeper mutation." (PMID 30409180, 2018). "Therefore, the detection of the EGFR mutation could be due to DNA fragments of ruptured tumour cells merging with interstices." (PMID 30029601, 2018). "However, the role of EGFR in metastases and the precise mechanisms underlying EGFR activation by the tumor-associated microenvironment are largely unknown." (PMID 30134822, 2018). "However, this therapeutic decision may be challenging when insufficient tumor tissue is available for EGFR mutation testing." (PMID 29623586, 2018). "For instance, N-glycosylated α5 integrin interacts with EGFR, promotes complex formation with α5β1 α6β4 heteropolymers and integrins, therefore, constitute proteins that may express mutated N-glycosylation sites in neoplastic diseases." (PMID 29541627, 2018). "However, in patients with brain metastases and EGFR-mutant tumors, the presence of exon 21 insertion was associated with significantly shorter survival (HR 2.52; 95% CI: 1.22–5.19; p = 0.01) when compared to patients with tumours harbouring exon 19 deletion." (PMID 29854298, 2018). "Genes implicated in angiogenesis and tumor hypoxia, particularly vascular endothelial growth factor, were associated with the degree of contrast enhancement, and a high ratio of contrast enhancing tumor to necrosis correlated with epidermal growth factor receptor overexpression." (PMID 29459844, 2018). "Once the major tumor burden has been destroyed and the risk of these side effects are low, UniCAR-modified T cells may be armed with the more risky TM such as the α-EGFR-EGFR TM which, however, allows the killing of tumor cells expressing low levels of the TAA." (PMID 29876011, 2018). "Thus, MR30 is a multifaceted molecule, which can be used under multiple contexts: (a) to exert selectivity for the HER family of oncogenes, (b) to induce potent growth inhibition in tumour cells with PTEN, K-RAS, B-RAF mutations and (c) to sensitize tumours that co-express EGFR and MGMT to TMZ." (PMID 30416678, 2018).
tumor (continued). "Thus, patients with EGFR mutations may benefit from a combination of anti-tumor immunologic therapy and an EGFR inhibitor, especially TKI-resistant individuals, although the causal relationship between TILs and EGFR mutations needs further evaluation." (PMID 29799009, 2018). "Also, since the epidermal growth factor receptor (EGFR) is known to play a pivotal role in tumor growth, we investigated whether EGFR was associated with the anti-proliferative effect of S5 on A375 cells." (PMID 30513793, 2018). "However, biopsy samples might be the only tumor material available for testing the EGFR mutation status in some cases, but these samples are often composed of variable ratios of tumor to normal cells." (PMID 30235778, 2018). "Therefore, we hypothesized that EGFR participates in maintaining the cancer stemness property as the leading cause of tumor recurrence." (PMID 28787001, 2017). "Emerging evidence has indicated that circulating tumor DNA (ctDNA) from plasma could be used to analyze EGFR mutation status for NSCLC patients; however, due to the low level of ctDNA in plasma, highly sensitive approaches are required to detect low frequency mutations." (PMID 28978074, 2017). "Interestingly, the recurrent tumours tend to lack expression of the EGFR variant after therapy." (PMID 28800767, 2017). "Beyond the outgrowth of mutant BRAF, we identified two additional genetic alterations in the resistant tumor that could contribute to EGFR TKI resistance: focal amplification of 7q31.2 encoding MET in the resistant tumor cells, a low frequency EGFRT790M mutation (14% variant frequency)." (PMID 28287179, 2017). "Therefore, increased apoptosis may serve as the major mechanism underlying tumor growth inhibition after treatment using combination therapy including an OXPHOS uncoupling agent with an EGFR-TKI." (PMID 28915593, 2017). "An additional explanation may be the EGFR mutation heterogeneity within the tumor." (PMID 28520821, 2017). "Collectively, these findings strongly suggest that Treg function might also play an important role in human tumor immune therapy, and we may assume that EGFR antagonist treatment-associated interference with Treg-mediated immune suppression enhances the efficacy of such cancer treatments." (PMID 28970798, 2017). "The differences in concentration between them and the p.T790M may confirm that the tumor is heterogeneous, and it is composed by 1) wild-type clones, 2) cells carrying both the EGFR activating and p.T790M mutations, 3) clones with only the original EGFR activating mutation." (PMID 29156777, 2017). "Recently, broad studies of tumor biology have allowed developing particular targeted therapies for patients with specific mutations in multiple driver genes, including the epidermal growth factor receptor (EGFR), anaplastic lymphoma kinase (ALK), as well as ROS proto-oncogene 1 (ROS1)." (PMID 28881856, 2017). "However, the additional analyses of tumor samples from our and others’ cohorts supported the correlation of EGFR-mutation status with vimentin expression, suggesting that EGFR-mutation status may be prone to undergo EMT-mediated cancer cell dissemination." (PMID 28881820, 2017). "Therefore, a combination therapy should address each cell type involved in linking the cellular tumorigenic network: The proliferation of malignant tumor cells can be effectively targeted at their driver mutations if present, such as for EGFR mutated tumors by EGFR TKIs." (PMID 28402937, 2017). "Of the 50 EGFR mutation positive plasma samples, 25 (50.0%) harbored single E19Dels, 21 (42.0%) single L858R mutation, 1 (2.0%) E20-ins mutation and 3 (6.0%) double mutations (2 E19Del + T790M, 1 L858R + T790M), suggesting a similar mutation profiling to the tumor tissues." (PMID 28829813, 2017).
tumor (continued). "Interestingly, when we compared the genomic profiles of the primary tumor and the first recurrence, we observed loss of the tumor cells harboring the activating EGFR A289V mutation, most likely due to the targeted anti-EGFR therapy with vandetanib, but preservation of EGFR amplification." (PMID 28153049, 2017). "Thus, the unresponsiveness of primary tumours in the right-sided colon to anti-EGFR antibodies in later line might be partially explained by underlying BRAFnon-V600E-mutated tumours." (PMID 28972961, 2017). "Notably, anti EGFR-specific IgA antibodies may overcome this obstacle, since they can engage tumor-associated myeloid cells for tumor cell killing." (PMID 28895886, 2017). "Also, as tumor tissue is gold standard to detect EGFR mutation, it should be collected as possible." (PMID 28107191, 2017). "Although total cfDNA isolated from serum vs plasma was not investigated in the current analysis, it is possible that the higher EGFR mutation detection rate observed in plasma vs serum may reflect a higher proportion of tumour-derived mutant cfDNA present in plasma." (PMID 28006816, 2017). "In addition to EGFR, another target set linked to major drug development programmes is the immune checkpoint PD-1 expressed on T cells, and its ligand PD-L1, expressed on tumour and antigen-presenting cells." (PMID 28597119, 2017). "In addition, because all patients included in LL3 and LL6 had tumour tissue that was positive for one or more EGFR mutation, we were unable to formally determine the sensitivity and specificity of the methods to detect these mutations, as compared with wild-type EGFR, in serum or plasma." (PMID 28006816, 2017). "Therefore, we conducted this retrospective study to determine whether advanced NSCLC patients with EGFR-sensitive mutations could benefit from MWA at primary tumor sites plus EGFR-TKIs when compared with EGFR-TKIs alone." (PMID 28915624, 2017). "Current studies demonstrated that various TAAs could act as target antigens for CAR-T cells, for instance, the type III variant epidermal growth factor receptor (EGFRvIII) was considered as an ideal target for its aberrant expression on the cell surface of several tumor types." (PMID 28356156, 2017). "Tumor mutation testing allows us to divide patients into three groups: patients with EGFR-positive tumor mutations (10–30%); patients with ALK rearrangements (4–7%); and patients with tumors who either do not have EGFR or ALK mutations, or their mutation status is unknown." (PMID 28373963, 2017). "However, the wait-time for the result of EGFR mutational analysis may be significant especially for those patients who are symptomatic with high tumor burden and require timely initiation of systemic therapy." (PMID 29232915, 2017). "However, there is variability in the detection rates of EGFR mutation in the blood compared with the standard methodology using tumour tissue, and the correlation of blood-derived EGFR mutation positivity with specific patient characteristics or clinical outcomes remains uncertain." (PMID 28006816, 2017). "Furthermore, gene sequencing cannot reflect EGFR mutation status in the whole tumor." (PMID 28489575, 2017). "Previous have demonstrated that activation of the EGFR signaling pathway contributes to many biological processes including cell survival, proliferation, apoptosis, differentiation, cell cycle progression, invasion, metastasis and angiogenesis, all of which are associated with tumor progression." (PMID 27437777, 2016). "However, even when only 267 patients whose tumor EGFR mutation status had been molecularly determined by standard methods were examined, clinicopathological features based on PD-L1 expression and PD-L1 copy number were similar to results from the entire cohort." (PMID 27050074, 2016).
tumor (continued). "The relatively high frequency of intratumor EGFR mutant alleles might imply that TKIs-sensitive mutant clones accounted for the major part of whole tumor clones, and needed longer time to develop drug resistance compared with the those with low frequency of intratumor EGFR mutant alleles." (PMID 26989078, 2016). "Moreover, KRAS mutations were found to be rare and all tumours were EGFR wild-type." (PMID 26844548, 2016). "However, the association between cfDNA and detection of EGFR mutations in tumor tissue remains unclear." (PMID 27081078, 2016). "The onset of EGFR resistance can trigger alternative signaling pathways through association with other receptor tyrosine kinases or G-protein coupled receptors (GPCRs) to maintain the tumor phenotype but these precise mechanisms remain only partially understood." (PMID 27716204, 2016). "For example, anti-EGFR therapy and monitoring of mutations in EGFR downstream effectors as biomarkers of resistance may have limited applicability in syCRC patients because of the genetic contribution of distinct clones from multiple tumours." (PMID 27377421, 2016). "Mutations that lead to EGFR overexpression or constitutive activation have been associated with a number of cancers (e.g. it is up-regulated in 60-80% of colorectal cancer), determining uncontrolled cell division and tumor proliferation, and they are correlated with poor prognosis." (PMID 27145373, 2016). "Furthermore, our results highlight the difference of the extent of EGFR T790M and other EGFR-activating mutations among tumor samples, which may indicate the heterogeneity of acquired mutations." (PMID 26572169, 2015). "However, how much extent these genes affect tumorigenicity, tumor progression, and resistance to EGFR-TKIs is difficult to assess, as some mutations may represent only passive alterations (passenger mutations)." (PMID 26572169, 2015). "In summary, the anti-tumor progression efficacy combined with the already clinically validated safety profile during clinical testing as a BTK kinase inhibitor makes ibrutinib a potentially useful drug candidate for first line treatment of EGFR primary mutation- driven NSCLC." (PMID 26375053, 2015). "Furthermore, tumour specimens are required in order to efficiently select patients based on EGFR mutation profiles, yet sometimes insufficient primary tumour tissue is available or else circumstances dictate that samples are difficult to obtain having led to EGFR gene mutation detection failures." (PMID 25918681, 2015). "In view of all these data, future clinical investigations need to include both cutaneous and tumor biopsies as they might help understanding whether and how the mechanism of action and efficacy of EGFR targeted therapies is linked to dose-limiting cutaneous reactions." (PMID 25918250, 2015). "Continuing with the EGFR example, a ‘driver vs wheel’ metaphor of a ‘run‐away 18‐wheeler truck’ can help to conceptualize the current appreciation of inter‐patient heterogeneity of molecular ‘oncogenic drivers’ (the gas pedal) and loss of tumor suppressors (the brakes)." (PMID 25557400, 2015). "However, we observed only a single tumor in which this was the case; moreover, the EGFR mutation (R574L) in this tumor (which also harbored a KRASG12V mutation) has not been previously identified as oncogenic, lies outside the kinase domain and hence is unlikely to be activating." (PMID 26047463, 2015). "However, assessment of EGFR mutation status depending on tumor tissues has many limitations." (PMID 26227959, 2015). "Reports of improved efficacy with panitumumab and cetuximab in patients with wild-type versus mutant or unknown KRAS exon 2 status led to the requirement for physicians to determine a patient’s tumor KRAS mutation status prior to starting treatment with EGFR inhibitors." (PMID 26491871, 2015).
tumor (continued). "It remains an open question, however, if the addition of an EGFR targeting antibody to chemotherapy is entirely useless in a patient harboring a subclonal mutation or if patients may derive some benefit since the unmutated tumor cells may still be targeted." (PMID 26059438, 2015). "Considering that the in vitro inhibition of the BRAF downstream target MEK also affected MGL ligand expression, we assume that activating mutations in members of the MAPK pathway other than BRAF, such as KRAS and EGFR, may also cause aberrations in tumor cell glycosylation." (PMID 26172302, 2015). "The study concluded that EGFR mutational pattern heterogeneity frequency is relatively low, more commonly observed in multiple lung tumors, and that 38,2% of heterogenous pattern patients showed a variable tumor response to EGFR TKIs, with frequent development of EGFR resistance." (PMID 26422230, 2015). "Likewise, EGFR expression has been associated with increased tumour aggressiveness." (PMID 24454858, 2014). "In addition, we observed that phosphorylation of Tyr845 and Tyr1068 of EGFR was regulated by CHIP, Tyr845 of EGFR could be associated with Src and is involved in tumor malignancy or resistance to EGFR-targeted therapy." (PMID 24722501, 2014). "In addition to the different pathological nature of primary tumor and metastases, the inconsistency in the identification of EGFR mutation may also be due to the sensitivity of the detection methods." (PMID 24398248, 2014). "Finally, the fact that p27Kip1-deficient cells overexpress EGFR raises the interesting possibility that tumours deficient in either or both tumour suppressors could benefit from a therapeutic approach combining chemotherapeutics with EGFR inhibitors." (PMID 25121353, 2014). "When immunostaining was present in greater than 5% of tumour cells, a significant association was found between the expression of EGFR and age (P = 0.022), and tumour site (P = 0.022), with a significantly higher number of patients over 70 years having EGFR positive tumours in the left colon." (PMID 24609222, 2014). "In addition to observation of angiostatic effects, additional mechanisms underlying EFEMP1's tumor suppression function that have since come to light include attenuation of EGFR/AKT-mediated growth signaling activities and reduction of MMP-induced cancer cell invasion." (PMID 25594013, 2014). "Consequently, tumours bearing a KRAS mutation are less likely to respond to anti-EGFR drugs." (PMID 24454858, 2014). "Therefore, targeting hyperactive Ras might control not only tumours spurred by this aberration but also those that are promoted by upstream events such as overexpressed and/or mutated hyperactive EGFR." (PMID 25228915, 2014). "Interestingly, the synergism between SRC and EGFR in PCa may be associated with a more aggressive tumor phenotype." (PMID 24797896, 2014). "Using this model, we designed experiments to assess whether T cells expressing third-generation chimeric antigen receptors (CARs) targeting the tumor-specific mutation of the epidermal growth factor receptor, EGFRvIII, would localize to and treat invasive intracerebral GBM." (PMID 24722266, 2014). "However the success of this method is constrained by strong background signal from the amplified wild-type (wt) EGFR allele, requiring a minimum acceptable tumour cell content of 50 % and high quality DNA, thus affecting its practical usefulness in NSCLC clinics." (PMID 23892415, 2013). "Moreover, EGFR is implicated in tumor-induced angiogenesis and metastasis." (PMID 23409107, 2013). "The response rate to gefitinib and erlotinib in patients with tumors exhibiting activating mutations of EGFR is approximately 75%, suggesting that these mutations, at least in part, may have caused malignant transformation and contribute in large to the tumor maintenance pathway." (PMID 23956990, 2013). "Therefore, the tumor clone bearing this EGFR mutation could have been potentially responsive to EGR-TKI therapy." (PMID 24279718, 2013).